RN7SL334P (RNA, 7SL, cytoplasmic 334, pseudogene)
Gene: Miscellaneous RNA gene on chromosome 6 (25,031,009 to 25,031,287, reverse strand). Ensembl gene ENSG00000244618.
Homologues: Orthologues: chimpanzee Metazoa_SRP (99% identical), macaque Metazoa_SRP (84% identical). Paralogues in human: RN7SL1 (83% identical), RN7SL2 (83% identical), RN7SL3 (81% identical), RN7SL408P (80% identical), RN7SL679P (80% identical), RN7SL126P (79% identical), RN7SL220P (79% identical), RN7SL45P (79% identical), RN7SL566P (79% identical), RN7SL769P (79% identical), RN7SL7P (79% identical), RN7SL88P (79% identical), and 704 more.